GRHL2 (grainyhead like transcription factor 2)
Description:
Transcription factor playing an important role in primary neurulation and in epithelial development. Binds directly to the consensus DNA sequence 5'-AACCGGTT-3' acting as an activator and repressor on distinct target genes (By similarity). During embryogenesis, plays unique and cooperative roles with GRHL3 in establishing distinct zones of primary neurulation. Essential for closure 3 (rostral end of the forebrain), functions cooperatively with GRHL3 in closure 2 (forebrain/midbrain boundary) and posterior neuropore closure (By similarity). Regulates epithelial morphogenesis acting as a target gene-associated transcriptional activator of apical junctional complex components. Up-regulates of CLDN3 and CLDN4, as well as of RAB25, which increases the CLDN4 protein and its localization at tight junctions (By similarity). Comprises an essential component of the transcriptional machinery that establishes appropriate expression levels of CLDN4 and CDH1 in different types of epithelia. Exhibits functional redundancy with GRHL3 in epidermal morphogenetic events and epidermal wound repair (By similarity). In lung, forms a regulatory loop with NKX2-1 that coordinates lung epithelial cell morphogenesis and differentiation (By similarity). In keratinocytes, plays a role in telomerase activation during cellular proliferation, regulates TERT expression by binding to TERT promoter region and inhibiting DNA methylation at the 5'-CpG island, possibly by interfering with DNMT1 enzyme activity. In addition, impairs keratinocyte differentiation and epidermal function by inhibiting the expression of genes clustered at the epidermal differentiation complex (EDC) as well as GRHL1 and GRHL3 through epigenetic mechanisms.
Synonyms: BOM; TFCP2L3; FLJ13782; DFNA28; ECTDS; PPCD4
Tractability: No criterion of Open Targets' tractability assessment is met for any kind of drug.
Gene: Protein-coding gene on chromosome 8 (101,492,439 to 101,669,726, forward strand). Ensembl gene ENSG00000083307.
Subcellular location: Nucleus; Membrane
Subcellular location (Human Protein Atlas): Nucleoplasm
Gene Ontology:
Molecular function: chromatin DNA binding; DNA-binding transcription activator activity; DNA-binding transcription activator activity, RNA polymerase II-specific; DNA-binding transcription factor activity; DNA-binding transcription factor binding; identical protein binding; protein binding; sequence-specific DNA binding; DNA-binding transcription factor activity, RNA polymerase II-specific; intronic transcription regulatory region sequence-specific DNA binding; RNA polymerase II cis-regulatory region sequence-specific DNA binding; chromatin binding
Biological process: bicellular tight junction assembly; cell adhesion; cell junction assembly; epithelial cell morphogenesis; keratinocyte differentiation; positive regulation of transcription by RNA polymerase II; regulation of transcription by RNA polymerase II; brain development; epithelium migration; lung epithelial cell differentiation; neural tube closure; neural tube development; epidermis development; positive regulation of DNA-templated transcription
Cellular component: cell-cell junction; membrane; nucleoplasm; nucleus; chromatin
Genetic constraint (gnomAD): Loss-of-function variants: 18 observed, 72.78 expected, observed/expected ratio (o/e) 0.25, 90% interval 0.17 to 0.37. The upper end of that interval is the gene's LOEUF score, 0.37, which puts it in group 1 of 6, group 1 being the genes least tolerant of losing a copy. Missense variants: 568 observed, 738.78 expected, observed/expected ratio (o/e) 0.77, 90% interval 0.72 to 0.82. Synonymous variants: 264 observed, 268.46 expected, observed/expected ratio (o/e) 0.98, 90% interval 0.89 to 1.09.
Gene-disease validity (ClinGen):
ClinGen rates the evidence that GRHL2 causes each of these diseases.
nonsyndromic genetic hearing loss (autosomal dominant): Definitive.
Homologues: Orthologues: chimpanzee GRHL2 (100% identical), macaque GRHL2 (99% identical), dog GRHL2 (96% identical), pig GRHL2 (96% identical), rabbit GRHL2 (96% identical), mouse Grhl2 (95% identical), rat Grhl2 (95% identical), guinea pig GRHL2 (92% identical), tropical clawed frog grhl2 (81% identical), zebrafish grhl2b (70% identical), zebrafish grhl2a (61% identical), Caenorhabditis elegans grh-1 (31% identical), and 1 more. Paralogues in human: GRHL1 (57% identical), GRHL3 (45% identical), TFCP2 (21% identical), UBP1 (20% identical), TFCP2L1 (18% identical).
Diseases named in the same sentence as GRHL2 in open-access papers:
GRHL2 is named in the same sentence as 117 diseases in open-access papers, as found by Europe PMC text mining. Sharing a sentence is not in itself a finding about the gene and the disease. The quoted sentences say what the papers report.
breast carcinoma (62 papers, 2012 to 2026). "Another study emphasized the correlation between GRHL2 and highly metastatic breast cancer cells, again reiterating unfavorable outcomes associated with increased GRHL2 expression." (PMID 39199676, 2024). "In summary, this work demonstrates that GRHL2, a key epithelial transcriptional regulator, can regulate extracellular adenosine levels produced by breast cancer cells through suppression of the gene encoding the NT5E/CD73 ecto-enzyme." (PMID 38706844, 2024). "Loss of GRHL2 was reported in gastric cancer and GRHL2 was found downregulated at the invasive front of breast cancers and loss of GRHL2 expression in primary breast cancers correlated with lymph node metastasis." (PMID 36691073, 2023). "By contrast, others have reported that high GRHL2 expression in breast cancer cell lines is associated with sensitivity to anoikis and chemotherapy and reduced tumor initiation capacity." (PMID 36691073, 2023). "Our findings corroborate such a role for GRHL2 and demonstrate an association of GRHL2 expression with poor prognosis in breast cancer." (PMID 36768838, 2023). "We addressed to what extent GRHL2 regulated gene clusters identified in our conditional MCF7 KO model predicted associations with GRHL2 gene expression in breast cancer patients." (PMID 36691073, 2023). "shRNA mediated knock-down of Grhl2 in breast cancer cells caused the down-regulation of Erbb3 resulting in lowered levels of cell proliferation and changes associated with EMT." (PMID 35269877, 2022). "PSFs such as GRHL2 associate with poor prognosis in breast cancer, motivating us toinvestigate the correlation of ESRP1 with patient survival rates." (PMID 31069317, 2018). "As an in vivo experiment-anchored mechanism, all gene markers were associated with Grhl2 expression in mouse models of murine and human breast cancer/epithelia cell lines." (PMID 23441166, 2013). "This research demonstrates a novel strategy to integrate both biological experiments and clinical gene expression profiles for extracting and elucidating the genomic impact of a novel factor, GRHL2, and its associated gene-sets on the breast cancer prognosis." (PMID 23441166, 2013). "Above all, these data indicate that Grhl2 is associated with an unfavorable outcome in breast cancer patients." (PMID 23284647, 2012). "To investigate if Grhl2 is associated with the epithelial phenotype in human breast cancers, we analyzed two microarray datasets of human breast cancer cell lines." (PMID 23284647, 2012). "Large clinical data also revealed that high levels of Grhl2 expression were significantly associated with poor relapse free survival and increased risk of metastasis in breast cancer patients." (PMID 23284647, 2012). "Large clinical datasets reveal that expression of Grhl2 is significantly associated with poor relapse free survival and increased risk of metastasis in breast cancer patients." (PMID 23284647, 2012). "However, at high levels, GRHL2 preferentially binds sites associated with motifs of transcription factors associated with breast cancer progression." (PMID 39199676, 2024). "Together, these data support the idea that the plasticity and properties induced by elevated GRHL2 may provide a selective advantage to explain the association between GRHL2 and breast cancer progression." (PMID 39199676, 2024). "Interestingly, while we similarly observed an increase in FOXA1 motifs at high levels of GRHL2, our studies indicate that GRHL2 binds near motifs associated with development in hormone-sensitive breast cancer cells." (PMID 39199676, 2024). "Given that high levels of GRHL2 were inducing multiple phenotypes associated with breast cancer progression, yet also enriching epithelial markers, we asked if a high GRHL2 expression may induce a plastic state observed during EMT." (PMID 39199676, 2024). "Furthermore, loss of GRHL2 expression in primary breast cancers is correlated with lymph node metastasis." (PMID 39430246, 2024).
breast carcinoma (continued). "Indeed, in prostate cancer, breast cancer, lung cancer and ovarian cancer downregulation of GRHL2 has been associated with the inhibition of cell proliferation." (PMID 36768838, 2023). "Notably, the gene clusters showing up- or downregulation in response to GRHL2 loss show a significant, albeit low level of correlation with GRHL2 expression in breast cancer patients." (PMID 36691073, 2023). "However, GRHL2 mRNA expression was negatively associated with overall survival in basal-like breast cancer patients." (PMID 36768838, 2023). "Here, we have explored whether luminal and basal A breast cancer cells that are GRHL2 positive and have an epithelial phenotype with E-cadherin-mediated cell-cell contacts, respond similarly to a loss of GRHL2." (PMID 36768838, 2023). "Altogether, these findings point to largely common but also distinct roles for GRHL2 in luminal and basal breast cancers with respect to growth and motility and indicate that, in agreement with its negative association with patient survival, growth suppression is the dominant response to GRHL2 loss." (PMID 36768838, 2023). "Using an unbiased approach, we identify the epithelial transcription factor grainyhead-like 2 (GRHL2) as a key co-regulator of PR activity in hormone responsive breast cancer cells." (PMID 41843622, 2026). "KDM4C regulates cathepsin L-mediated histone H3 N-terminal tail clipping through grainyhead-like 2 (GRHL2) methylation in breast cancer." (PMID 40457074, 2025). "Results obtained by immunohistochemical analysis of GRHL2 expression in primary breast cancers support an important role of GRHL2 subnuclear compartmentalization in breast carcinogenesis." (PMID 40889682, 2025). "The subnuclear distribution of GRHL2 in primary breast cancers was analyzed using a tissue microarray with more than 2000 specimens and a GRHL2-specific antibody." (PMID 40889682, 2025). "The formation of GRHL2 aggresome-like structures occurred also in breast cancer cells and indicates participation of GRHL2 proteins in a quality control pathway described recently." (PMID 40889682, 2025). "The role of GRHL2 in breast cancer is ambiguous, with previous studies showing both pro- and anti-metastatic effects." (PMID 39780291, 2025). "We next analyzed the distribution of GRHL2 in breast cancer cell lines by indirect immunofluorescence staining and found that GRHL2 mostly was dispersed in the nucleoplasm of cells." (PMID 40889682, 2025). "Considering the many known limitations of gene expression analyses using omics-based datasets and the heterogeneous subnuclear distribution in breast cancer cells, more elaborated GRHL2 protein expression analyses are needed." (PMID 40889682, 2025). "Here, GRHL2 has been shown to cooperate with androgen receptor in prostate cancer and with estrogen receptor α in breast cancer by acting as a pioneer factor facilitating chromatin accessibility." (PMID 40889682, 2025). "Here we identified the GRHL2 transcription factor as a chromatin recruiter of CTSL in KDM4C-amplified basal breast cancer cells." (PMID 40457074, 2025). "Loss of GRHL2, through enhanced CD73 expression, stimulates CD8+ T cell migration toward breast cancer cells." (PMID 38706844, 2024). "The luminal-specific TF EHF is a target of GRHL2 that is conserved in luminal breast cancer cell lines." (PMID 39545637, 2024). "In contrast, here we examine how increases in breast cancer cell GRHL2 protein concentration altered DNA binding." (PMID 39199676, 2024). "Alternatively, binding sites in cells expressing high levels of GRHL2 showed nearby FOX and Tcf12 motifs, which are associated with tumor progression in the context of breast cancer." (PMID 39199676, 2024). "Primary mammosphere formation assays were next assessed to determine if high levels of GRHL2 promoted self-renewal of breast cancer cells." (PMID 39199676, 2024).
breast carcinoma (continued). "Some authors report that GRHL2 exhibits important roles in hormone-dependent cancer, such as luminal breast cancer, affecting EMT processes and tumor progression." (PMID 39208653, 2024). "Elevated GRHL2 can play a disproportionate role in breast cancer progression with the coexistence of stem cell and dormancy behaviors supporting cellular plasticity for tumor initiation and resistance for ER-positive breast cancer cells." (PMID 39199676, 2024). "Collectively, these studies highlight the significant role of GRHL2 in the pathology of ER+/HER2− breast cancer." (PMID 38429368, 2024). "FOXA1 functions as a pioneer factor for ER, promoting luminal-lineage proliferation, whereas GRHL2 is known to be involved in reprogramming ER signaling in breast cancer development." (PMID 38429368, 2024). "Taken together, in agreement with the findings in the MCF-7 conditional KO model, these findings indicated that NT5E/CD73 is negatively correlated with GRHL2 in human breast cancer cell lines and breast cancer patients." (PMID 38706844, 2024). "High levels of the transcription factor Grainyhead-like protein 2 (GRHL2) contribute to worse outcomes for patients with breast cancer tumors that express estrogen receptor (ER)." (PMID 39199676, 2024). "Our finding that NT5E/CD73 is inversely correlated with GRHL2 in breast cancer cell lines and in patient tumors or tumor areas suggests the negative regulation of CD73 by GRHL2 in breast cancer is common." (PMID 38706844, 2024). "In this study, we uncovered that well-known TFs, FOXA1 and GRHL2 are key epigenetic regulators distinguishing the diversity of genome-wide chromatin accessibility pattern across breast cancer cell lines." (PMID 38429368, 2024). "In studies of phosphorylated ER (pER), an activated form of ER present in both primary and metastatic breast cancers, our group identified the nuclear transcription factor Grainyhead-like protein 2 (GRHL2) as a cooperating factor." (PMID 39199676, 2024). "The presence of an EMT hybrid state induced by high GRHL2 expression is consistent with dormancy and the enrichment of stem cell-like characteristics in breast cancer cells." (PMID 39199676, 2024). "Using multiple methods to increase GRHL2 expression in breast cancer cells, we found that high GRHL2 promotes both epithelial and mesenchymal phenotypes." (PMID 39199676, 2024). "Our previous research has also shown that GRHL2 contributes to the epigenetic intratumor heterogeneity of ER+/HER2− breast cancer." (PMID 38429368, 2024). "Although previous research suggests that both FOXA1 and GRHL2 play a crucial role in the development and progression of breast cancer, there is limited understanding of their upstream regulators." (PMID 38429368, 2024). "We show that elevated GRHL2 in an ER-positive breast cancer cell background resulted in the simultaneous expression of both epithelial and mesenchymal markers in the same cell." (PMID 39199676, 2024). "In summary, our study provides insight into the epigenetic heterogeneity in breast cancer cell lines as well as the roles of FOXA1 and GRHL2 in shaping breast cancer properties." (PMID 38429368, 2024). "We explore genome wide GRHL2 binding sites conserved in three ER⍺/GRHL2 positive luminal breast cancer cell lines by ChIP-Seq." (PMID 36691073, 2023). "In the GSM2970418 data including the breast cancer cell and epithelium, the regulatory score was 1.735 of GRHL2 for SCIN." (PMID 38201443, 2023). "GRHL2 acts as an essential transcription factor for epithelial-to-mesenchymal transitions and estrogen-induced transcription in breast cancer." (PMID 37076890, 2023). "Recent studies have shown that GRHL2 cooperates with androgen receptor in prostate cancer and with ER⍺ in breast cancer." (PMID 36691073, 2023). "Integration of ChIP- and Bru-seq pinpoints candidate direct GRHL2 target genes in luminal breast cancer." (PMID 36691073, 2023).